RNU6-583P (RNA, U6 small nuclear 583, pseudogene)
Gene: Small nuclear RNA gene on chromosome 4 (127,891,991 to 127,892,082, forward strand). Ensembl gene ENSG00000251821.
Homologues: Orthologues: chimpanzee U6 (99% identical), guinea pig U6 (75% identical), mouse Gm22335 (75% identical). Paralogues in human: RNU6-1019P (88% identical), RNU6-116P (88% identical), RNU6-480P (88% identical), RNU6-11P (87% identical), RNU6-1251P (87% identical), RNU6-34P (87% identical), RNU6-37P (87% identical), RNU6-832P (87% identical), RNU6-83P (87% identical), RNU6-959P (87% identical), RNU6-1060P (86% identical), RNU6-1075P (86% identical), and 1288 more.